ENSG00000288683 (novel protein, PEX26-TUBA8)
Gene: Protein-coding gene on chromosome 22 (18,077,989 to 18,131,720, forward strand). Ensembl gene ENSG00000288683.
Genetic constraint (gnomAD): Missense variants: 379 observed, 379.3 expected, observed/expected ratio (o/e) 1, 90% interval 0.92 to 1.09. Synonymous variants: 180 observed, 162.1 expected, observed/expected ratio (o/e) 1.11, 90% interval 0.98 to 1.26.